LINC00330 (long independently transcribed non-coding RNA 330)
Synonyms: NCRNA00330
Gene: Long non-coding RNA gene on chromosome 13 (44,799,503 to 44,809,630, reverse strand). Ensembl gene ENSG00000235097.
Diseases named in the same sentence as LINC00330 in open-access papers:
LINC00330 is named in the same sentence as 3 diseases in open-access papers, as found by Europe PMC text mining. Sharing a sentence is not in itself a finding about the gene and the disease. The quoted sentences say what the papers report.
tumor (3 papers, 2018 to 2024). "The analysis of ESCC clinical samples indicated that in the majority of tumor tissues with low expression of LINC00330, there was a significant increase in CD68+ TAM infiltration." (PMID 38769475, 2024). "Our analysis suggests that LINC00330 regulates the expression of numerous BCa-related mRNAs through interactions with miRNAs involved in the regulation of tumor progression, including miR-195 and miR-145." (PMID 30170380, 2018). "LINC00330 is a poorly characterized intergenic long noncoding RNA, and only a few reports have suggested that LINC00330 may be a key regulator of tumor origin and progression and has potential as a prognostic biomarker." (PMID 38769475, 2024). "In the prognostic PRlncRNA risk model, 8 lncRNAs (HOTAIR, LINC00402, SFTA1P, LINC00461, DSCR8, CYP1B1-AS1, LINC00330, ALMS1-IT1) were upregulated, while the other 3 lncRNAs (ZRANB2-AS1, MYB-AS1, TP53TG1) were downregulated in tumor tissues." (PMID 35413978, 2022). "Similarly, LINC00330 expression was assessed in the cancerous and adjacent normal tissues of 22 patients with ESCC who were pathologically diagnosed and underwent tumor resection surgery." (PMID 38769475, 2024). "In contrast, sh-LINC00330 in M1 cells significantly promoted ESCC cell growth, inhibited apoptosis, and enhanced tumor cell invasion." (PMID 38769475, 2024). "In conclusion, the study highlights the role of LINC00330 as a key inhibitor in the development of ESCC and demonstrates its ability to inhibit tumor progression both in vitro and in vivo, suggesting its potential as a therapeutic target and biomarker for ESCC treatment." (PMID 38769475, 2024).
infection (1 paper, 2024). The state of being infected such as from the introduction of a foreign agent such as serum, vaccine, antigenic substance or organism. "Overexpression and knockdown of LINC00330 in ESCC cell lines were achieved by transient transfection or lentiviral packaging and infection, followed by a series of gain-of-function and loss-of-function experiments." (PMID 38769475, 2024).
LINC00330 also shares sentences with these, for which no sentence is quoted: esophageal cancer (1 paper).